ATXN7 (ataxin 7)
Description:
Acts as a component of the SAGA (aka STAGA) transcription coactivator-HAT complex. Mediates the interaction of SAGA complex with the CRX and is involved in CRX-dependent gene activation. Probably involved in tethering the deubiquitination module within the SAGA complex. Necessary for microtubule cytoskeleton stabilization. Involved in neurodegeneration.
Synonyms: SCA7; OPCA3; ADCAII; SGF73
Tractability: PROTAC: UniProt records ubiquitination sites on it; ubiquitination databases record sites on it.
Gene: Protein-coding gene on chromosome 3 (63,863,155 to 64,003,558, forward strand). Ensembl gene ENSG00000163635.
Subcellular location: Nucleus (Isoform a); Nucleus, nucleolus; Nucleus matrix; Cytoplasm, cytoskeleton; Cytoplasm (Isoform b)
Subcellular location (Human Protein Atlas): Cytosol; Nucleoplasm
Pathways (Reactome):
Chromatin organization: HATs acetylate histones
Metabolism of proteins: Ub-specific processing proteases
Gene Ontology:
Molecular function: protein binding; chromatin binding
Biological process: microtubule cytoskeleton organization; negative regulation of microtubule depolymerization; regulation of transcription by RNA polymerase II; nucleus organization; positive regulation of DNA-templated transcription; positive regulation of transcription by RNA polymerase II; regulation of DNA repair; regulation of RNA splicing; visual perception
Cellular component: cytoplasm; cytosol; microtubule cytoskeleton; nuclear matrix; nucleoplasm; nucleus; SAGA complex; transcription factor TFTC complex; cytoskeleton; nucleolus
Genetic constraint (gnomAD): Loss-of-function variants: 10 observed, 66.02 expected, observed/expected ratio (o/e) 0.15, 90% interval 0.092 to 0.26. The upper end of that interval is the gene's LOEUF score, 0.26, which puts it in group 1 of 6, group 1 being the genes least tolerant of losing a copy. Missense variants: 1,220 observed, 1,136 expected, observed/expected ratio (o/e) 1.07, 90% interval 1.02 to 1.13. Synonymous variants: 484 observed, 449.22 expected, observed/expected ratio (o/e) 1.08, 90% interval 1 to 1.16.
Homologues: Orthologues: chimpanzee ATXN7 (98% identical), macaque ATXN7 (97% identical), rabbit ATXN7 (93% identical), pig ATXN7 (91% identical), dog ATXN7 (85% identical), guinea pig ATXN7 (85% identical), mouse Atxn7 (84% identical), rat Atxn7 (83% identical), tropical clawed frog atxn7 (59% identical), zebrafish atxn7 (47% identical). Paralogues in human: ATXN7L1 (37% identical), ATXN7L2 (25% identical), ATXN7L3 (9% identical), ATXN7L3B (1% identical).
Diseases named in the same sentence as ATXN7 in open-access papers:
ATXN7 is named in the same sentence as 106 diseases in open-access papers, as found by Europe PMC text mining. Sharing a sentence is not in itself a finding about the gene and the disease. The quoted sentences say what the papers report.
Ataxia (52 papers, 2009 to 2026). Ataxia refers to impaired coordination of voluntary muscle movement. "Selective overexpression of mutated ataxin-7 in animal models has been associated with selective loss of vulnerable subsets of neurons, associated with progressive ataxia, retinal and cerebellar pathology, and early death." (PMID 39139632, 2024). "In particular, the repeat length of ATXN7 (SCA7), whose expansion is associated with progressive cerebellar ataxia and retinopathy, was normal (10/12 repeats)." (PMID 39596509, 2024). "Here, we present a novel spinocerebellar ataxia variant occurring in a patient with mutations in both ATXN7 and TOP1MT, which encodes mitochondrial topoisomerase I (top1mt)." (PMID 35422034, 2022). "Here, we identify a novel spinocerebellar ataxia variant, occurring in a patient with mutations in both ataxin-7 and top1mt." (PMID 35422034, 2022). "The clinical, molecular, and functional data presented in this study provide evidence for a previously unreported spinocerebellar ataxia variant, occurring in a patient with concomitant mutations within ataxin-7 and top1mt." (PMID 35422034, 2022). "To recapitulate the cause for spinocerebellar ataxia, we must look at mutations in ataxin-7 and top1mt concurrently." (PMID 35422034, 2022). "Our RNASeq analysis revealed that the spinocerebellar ataxia–associated gene ataxin 7 (ATXN7) is expressed in the corneal endothelium, which suggests the possibility of a mechanism of disease similar to that found in FECD and DM1." (PMID 30025114, 2018). "Among these, SORBS1 physically interacts with ATXN7, an autosomal dominant gene causing cerebellar ataxia." (PMID 23028291, 2012). "Our work suggests that ataxin-7 may have important interactions with the cellular energetic machinery and provides insight into the phenotype of a new spinocerebellar ataxia variant." (PMID 35422034, 2022). "Spinocerebellar ataxia type 7 (SCA7) is a neurodegenerative disease characterized by cerebellar ataxia and retinal degeneration, caused by an abnormal expansion of CAG repeats at the ATXN7 gene." (PMID 41596334, 2026). "We observed that an earlier age of ataxia onset correlated with longer ATXN7 CAG repeat expansions (Spearman r = −0.8598, p = 0.0023, N = 10), analogous to previously published studies." (PMID 40507882, 2025). "Spinocerebellar ataxia type 7 (SCA7) is an inherited neurodegenerative disease characterized by cerebellar ataxia and retinal degeneration, caused by an abnormal expansion of the CAG trinucleotide in the coding region of the ATXN7 gene." (PMID 40136424, 2025). "Two are in genes associated with spinocerebellar ataxia (ATXN3, ATXN7), while one is in FAM3A, encoding a cytokine-like protein that has been associated with modulation of PI3K signalling." (PMID 37974153, 2023). "In summary, we show that concurrent mutations within ATXN7 and TOP1MT are associated with a novel spinocerebellar ataxia variant." (PMID 35422034, 2022). "Our work provides important insight into the cellular biology of ataxin-7 and top1mt and offers insight into the pathogenesis of spinocerebellar ataxia applicable to multiple subtypes of the illness." (PMID 35422034, 2022). "Abnormally long polyQ tract in the ataxin 7 (ATXN7) gene primarily manifests as cerebellar ataxia in SCA7." (PMID 34277598, 2021). "Spinocerebellar ataxia type 7 (SCA7), a neurodegenerative disease characterized by cerebellar ataxia and retinal degeneration, is caused by an abnormal CAG repeat expansion in the ATXN7 gene coding region." (PMID 32138195, 2020). "SCA7, caused by a polyQ expansion in ataxin-7, is the only SCA belonging to ADCA type 2 characterized by progressive cerebellar ataxia and concomitant retinal degeneration." (PMID 32973440, 2020). "The spinocerebellar degeneration, atrophy of pyramidal tracts and motor nuclei in the brainstem, retinal degeneration, and ataxin-7 immunoreactive neuronal intranuclear inclusion are involved in the pathology of SCA7." (PMID 32973440, 2020).
Ataxia (continued). "Correlative findings include loss of GLAST and reduced astroglial glutamate uptake when mutant ataxin-7 is solely expressed in Bergmann glia with this mouse displaying ataxia and Purkinje cell death." (PMID 28173092, 2016). "SCA7 is the result of an expansion in the N-terminal region of the ATXN7 gene, patients exhibit ataxia as well as retinal dysfunction." (PMID 26733936, 2015). "For ataxias SCA1, SCA2, SCA3, SCA6, SCA7, SCA17 and dentatorubral-pallidoluysian atrophy, expansion beyond 39, 33, 45, 20, 34, 41, and 35 repeats in the ATXN1, ATXN2, ATXN3, CACNA1A, ATXN7, TBP, and ATN1 genes, respectively, will cause disease." (PMID 35592702, 2022). "Mendelian diseases have been studied in the spectrum of protein–protein interactions, with a study on the two ataxia disease-causing genes ATXN7 and CACNA1A that identified new protein partners that may explain comorbidity of ataxia with other genetic diseases such as macular degeneration." (PMID 37298131, 2023). "Of note, the child’s parents had been well at the time WGS was completed for the proband but 2 years after this, her father presented with ataxia and was subsequently also found to have a heterozygous CAG repeat expansion in ATXN7." (PMID 39349043, 2025). "This study involved six genes (ATXN1, ATXN3, ATXN7, HTT, NOP56, and PPP2R2B), while a higher detection rate has been reported in a spinocerebellar ataxia cohort (4.4%, 22/498), which included five genes (ATXN2, ATXN3, NOP56, AR and HTT)." (PMID 38308084, 2024). "In patients with cerebellar signs, 6 of 9 were screened for the common spinocerebellar ataxia genes including ATXN1 (SCA 1), ATXN 2 (SCA2), ATXN3 (SCA3) and ATXN7 (SCA7)." (PMID 39113437, 2024). "The frequency is followed by ATXN7: 6.09%, TBP: 5.59%, ATXN2: 5.03%, CACNA1A: 4.28%, PPP2R2B: 2.68%, and ATXN3: 2.42% with respective cutoff values in uncharacterized ataxia cases." (PMID 36618024, 2022). "In humans, polyglutamine (polyQ) expansion in ATXN7 results in SCA7, a dominant neurodegenerative disorder distinguished from other ataxias by retinopathy." (PMID 27261002, 2016). "A child under the age of 5 presented with ataxia and global developmental delay was found to have a large repeat expansion of 120 CAG repeats in ATXN7 consistent with early-onset SCA7 after bioinformatic analysis of multiple loci using ExpansionHunter applied to WGS data." (PMID 39349043, 2025). "Similar pieces of evidence of non-cell autonomous neurodegeneration were also obtained in a SCA7 mouse model where the expression of the mutant ATXN7 gene in all cells but not in PCs led to ataxia and PCs degeneration." (PMID 32168822, 2020). "Combining ATXN7 100 CAG with loss of one Gcn5 allele led to additional degeneration, but these effects were more additive than synergistic, and additional cell loss caused by Gcn5 heterozygosity was not sufficient to cause severe cerebellar ataxia." (PMID 35401096, 2022). "Although the deletion of the mutant ATXN7 gene solely in BG was not sufficient per se to prevent the development of ataxia and neurodegeneration, its excision from BG in combination with PCs and inferior olivary (IO) neurons yielded a synergistic effect on the delay of symptoms onset." (PMID 32168822, 2020). "Notably, polyQ-expanded ATXN7 reduces SAGA deubiquitinase activity in vivo; thus, defects in ubH2B deubiquitination could induce the retinal degeneration that is unique to this ataxia." (PMID 27261002, 2016). "Given that ATXN2 and ATXN7 have not been described to act through Cic, it is tempting to speculate that the ion channel module we have identified represents an important shared pathway for Purkinje neuron pathology in many spinocerebellar ataxias." (PMID 32964235, 2020).
spinocerebellar ataxia type 7 (34 papers, 2011 to 2025). "SpinoCerebellar Ataxia type 7 (SCA7) is an inherited disorder caused by CAG triplet repeats encoding polyglutamine expansion in the ATXN7 protein, which is part of the transcriptional coactivator complex SAGA." (PMID 38227598, 2024). "A polyglutamine expansion in human DUB module subunit ATXN7, which gives rise to the neurodegenerative disease Spinocerebellar ataxia type 7 (SCA7), causes a significant decrease in SAGA acetyltransferase activity." (PMID 36965704, 2023). "A CAG expansion in AR causes spinal and bulbar muscular atrophy; an expansion in ATXN7 causes spinocerebellar ataxia type 7." (PMID 36071529, 2022). "Spinocerebellar ataxia type 7 (SCA7) is a neurodegenerative disease caused by a genomic expansion of trinucleotide CAG repeats encoding polyglutamine (polyQ) in ATXN7." (PMID 36251631, 2022). "CAG triplet expansion in ATXN7 results in a polyglutamine expansion in ATXN7 that causes spinocerebellar ataxia type 7 (SCA7), a progressive neurodegenerative disease characterized by degeneration of the spinocerebellar tract and the retinas." (PMID 35159365, 2022). "The CAG repeat expansion in the ataxin-7 gene (ATXN7) causes spinocerebellar ataxia type 7 - a mutation that results in the degeneration of the brain stem cells, retina and cerebellum." (PMID 33995769, 2021). "Spinocerebellar ataxia type 7 (SCA7) is an autosomal-dominant neurodegenerative disorder caused by a CAG repeat expansion in the coding region of the ataxin-7 gene." (PMID 34160002, 2021). "Spinocerebellar ataxia type 7 (SCA7) is an inherited neurodegenerative disease caused by a polyglutamine repeat expansion in the ATXN7 gene." (PMID 33626063, 2021). "Ataxin-7 (Atx7) is a disease-related protein associated with the pathogenesis of spinocerebellar ataxia 7, while its polyglutamine (polyQ) tract in N-terminus is the causative source of aggregation and proteinopathy." (PMID 31097749, 2019). "For example, lnc-sca7 (ATXN7L3B) is highly conserved in the central nervous system of human and adult mice and transcriptionally regulates the expression of ATXN7, which is the pathogenic gene of Spinocerebellar Ataxia Type 7 (SCA7)." (PMID 31249598, 2019). "A component of the SAGA DUB module, Ataxin 7 (Sgf73 in yeast), has been linked to an autosomal neurodegenerative disease called spinocerebellar ataxia 7 (SCA7)." (PMID 27057639, 2016). "Spinocerebellar ataxia type 7 (SCA7) is a human neurodegenerative polyglutamine (polyQ) disease caused by a CAG repeat expansion in the open reading frame of the ATXN7 gene." (PMID 27999335, 2016). "Expansions in ATXN7 cause spinocerebellar ataxia type 7, but the role of other kinds of mutations (nonsynonymous substitutions or deletions) in this gene in nervous system disorders is not yet well understood." (PMID 26075115, 2015). "Spinocerebellar ataxia type 7 (SCA7) is caused by a toxic polyglutamine expansion in the N-terminus of the protein ataxin 7 (ATXN7)." (PMID 24865773, 2014). "In humans, mutations in the DUB subunit ATXN7 are associated with the development of spinocerebellar ataxia type 7, a disease characterized by the loss of motor control as well as retinal defects." (PMID 25006164, 2014). "Spinocerebellar ataxia type 7 (SCA7) is a neurodegenerative disease caused by expansion of a CAG repeat within the gene encoding ataxin-7." (PMID 26331028, 2014). "Spinocerebellar ataxia type 7 (SCA7) is caused by a polyQ expansion in the ATXN7 gene." (PMID 41277874, 2025). "Spinocerebellar ataxia type 7 (SCA7) is an inherited neurodegenerative disease caused by a CAG repeat expansion in the ATXN7 gene." (PMID 33626063, 2021). "The human counterpart of Sgf73 is ataxin‐7, and the gene encoding this protein causes the autosomal dominant neurodegenerative disorder spinocerebellar ataxia type 7 (SCA7), upon CAG–polyglutamine repeat expansion." (PMID 28568901, 2017).
spinocerebellar ataxia type 7 (continued). "Spinocerebellar Ataxia type 7, which is a consequence of a polyglutamine expansion in the human homolog of the Sgf73 DUB module subunit, Ataxin-7, was reported to reduce the SAGA HAT module’s acetyltransferase activity." (PMID 36965704, 2023). "CAG-expanded ATXN7 has been previously defined in the pathogenesis of spinocerebellar ataxia type 7 (SCA7), a polyglutamine expansion autosomal dominant cerebellar ataxia." (PMID 35422034, 2022). "In that regard, the IFN component of the ATL therapeutic regimen effectively induces the clearance of mutant ataxin-7 from the brains of spinocerebellar ataxia 7 (SCA7) mouse models, resulting in clinically relevant neurological improvements." (PMID 35269436, 2022). "Moreover, the same study showed that NELL2 interacts with ATAXIN7 (ATXN7, MIM 607640), the causative gene for spinocerebellar ataxia type 7 (SCA7)." (PMID 31963867, 2020). "Spinocerebellar ataxia type 7 (SCA7) is a polyglutamine expansion ADCA which occurs as a result of a CAG repeat expansion within the first exon of the ATXN7 gene, located on chromosome 33,4." (PMID 35422034, 2022). "An example of this is Spinocerebellar ataxia type 7 (SCA7) which results from CAG-trinucleotide expansion of the ATXN7 gene, leading to polyglutamine expansion of the ATXN7 protein." (PMID 35159365, 2022). "A hallmark of the neurodegenerative disease spinocerebellar ataxia type 7 (SCA7) is the intranuclear accumulation of mutant, misfolded ataxin-7 (polyQ-ATXN7)." (PMID 30559154, 2019). "Spinocerebellar ataxia type 7 (SCA7) is a progressive neurodegenerative disorder resulting from abnormal expansion of an uninterrupted polyglutamine (polyQ) repeat in its disease protein, ataxin-7 (ATXN7)." (PMID 38906973, 2024). "Sgf73, a core component of SAGA, is the yeast orthologue of ataxin‐7, which undergoes CAG–polyglutamine repeat expansion leading to the human neurodegenerative disease spinocerebellar ataxia type 7 (SCA7)." (PMID 28568901, 2017).
Huntington disease (31 papers, 2005 to 2026). Huntington disease (HD) is a rare neurodegenerative disorder of the central nervous system characterized by unwanted choreatic movements, behavioral and psychiatric disturbances and dementia. "Specific silencing in cellular models has also been reported to SNPs targeting ataxin-7 in SCA7 and huntingtin in Huntington's disease." (PMID 23349684, 2013). "SCA7 is caused by the abnormal expansion of CAG triplet repeats encoding a polyglutamine (polyQ) tract in ATAXIN-7 (ATXN7), and therefore belongs to the group of CAG/polyQ expansion disorders, which includes Huntington’s disease (HD) and other SCAs (SCA1-3, 6 and 17)." (PMID 38227598, 2024). "SCA7 is caused by the expansion of a CAG repeat encoding a polyglutamine (polyQ) tract in ATAXIN-7 (ATXN7), and hence belongs to the family of 9 polyQ neurodegenerative disorders, which include 5 other SCAs (SCA1, SCA2, SCA3, SCA6 and SCA17) and Huntington’s disease (HD)." (PMID 36539812, 2022).
retinal degeneration (17 papers, 2014 to 2026). Degeneration of the retina. "It has been postulated that retinal degeneration in SCA7 may be associated with an abnormal interaction between the expanded ataxin-7 and CRX as potentially binding the expanded polyQ tract in ataxin-7 to a glutamine-rich region in CRX." (PMID 32973440, 2020). "In Drosophila, loss of Atxn7 leads to a phenotype similar to overexpression of the polyQ-expanded amino terminal truncation of human Atxn7 – reduced life span, reduced mobility, and retinal degeneration." (PMID 31348003, 2019). "In the Drosophila model of sca7, expression of expanded human ATXN7 induces retinal degeneration, neuronal apoptosis, ommatidial disorganization, and reduced electrophysiological response to light." (PMID 41002431, 2025). "Coincidently, loss of ATXN7 phenocopies SCA7 in Drosophila, causing neural and retinal degeneration." (PMID 35401096, 2022). "In Drosophila, ATXN7 loss mimics the phenotypes generated by overexpression of a polyglutamine-expanded amino-terminal truncation of human ATXN7: reduced life span, reduced mobility, and retinal degeneration." (PMID 35159365, 2022). "Cumulatively our data suggest that non-allele specific silencing of ataxin-7 in the retina by RNAi may be a viable therapeutic strategy in patients with SCA7 retinal degeneration." (PMID 24759684, 2014). "Expansion of a polyglutamine tract in ATXN7 (PolyQ-ATXN7) results in SCA7, a disease that is characterized by cerebellar and retinal degeneration." (PMID 34112237, 2021). "The interaction between ATXN7 and CRX has been hypothesised to be a key factor behind the development of retinal degeneration in SCA7 patients." (PMID 33626063, 2021). "The degree of retinal degeneration may vary depending on the stage of the disease course and the number of CAG repeats in the ataxin-7 gene." (PMID 32973440, 2020). "In SCA7, the degree of retinal degeneration may vary from normal fundus, occult macular dystrophy, cone-rod dystrophy to severe atrophy depending on when the disease course was observed and the length of CAG repeats in the ATXN7 gene." (PMID 32973440, 2020).
Machado-Joseph disease (10 papers, 2009 to 2025). "The most frequent SCA worldwide are those caused by CAG repeat expansions, as SCA1 (in ATXN1), DRPLA (ATN1), SCA2 (ATXN2), Machado-Joseph disease (MJD)/ SCA3 (ATXN3), SCA6 (CACNA1A), SCA7 (ATXN7), and SCA17 (TBP), usually designated polyglutamine (polyQ) ataxias." (PMID 39048885, 2024).